IGF1 (insulin like growth factor 1)
Diseases named in the same sentence as IGF1 in open-access papers (continued):
Sharing a sentence is not in itself a finding about the gene and the disease.
Hyperglycemia (continued). "It is known that IGFBP-3 is involved in hyperglycemia, glucose intolerance, and IR, but these effects cannot be explained by circulating free IGF-1 levels." (PMID 29112142, 2017). "Previous study showed that IGF-1 can inhibit mesangial cell apoptosis and hyperglycemia-induced DNA damage and promote DNA repair via activating IGF-1R signaling." (PMID 26986757, 2016). "Premature delivery (low gestational age and low birth weight), high oxygen supplementation, poor postnatal weight gain, hyperglycaemia, low IGF-1 concentration, blood transfusion and infection are associated with development of ROP20." (PMID 27982102, 2016). "It has been recently reported that a postprandial hyperglycemia in patients with Laron Syndrome was due to chronic IGF-1 deficiency and was reversed by IGF-1 replacement therapy." (PMID 26467524, 2015). "Maternal hyperglycemia stimulates fetal pancreatic hypertrophy and increase in fetal growth factors such as fetal insulin and insulin-like growth factor-1 (IGF-1) and leads to increased birth weight." (PMID 26831549, 2015). "Adult KK-Ay mice not only exhibited hyperglycaemia, hyperinsulinaemia as well high plasma IGF-1, but also showed higher TRB3 expression in the liver and lungs compared with C57 BL/6 mice." (PMID 26268733, 2015). "Hyperglycemia indirectly influences cancer cells through upregulation of insulin/IGF-1 and inflammatory cytokines in circulation." (PMID 26443426, 2015). "Hyperglycemia induced by the intake of these beverages and foods stimulates high insulin secretions, which act per se as a growth factor and induce an increase of IGF-1 (insulin-like growth factor)." (PMID 26649040, 2015). "In fact, IGF-1 has been used experimentally to treat hyperglycemia of both type 1 and type 2 diabetes." (PMID 26514337, 2015). "Treatment with IGF1 attenuated hyperglycemia-induced apoptosis by 68% (3.23 ± 0.76% vs. 9.97 ± 1.29%; P < 0.001; n = 3) in comparison with the non-treated control." (PMID 24910802, 2014). "Since there is significant cross-talk between leptin receptor, insulin, and IGF1R/IGF1 (insulin-like growth factor) signaling pathways, we assessed the effect of hyperglycemia on key intermediates within each of these pathways." (PMID 24260287, 2013). "In essence, obese individuals with hyperinsulinaemia and hyperglycemia will have higher concentrations of free circulating IGF-1 and augmented activation of the IGF-dependent proliferation pathway." (PMID 23983688, 2013). "The most important finding of this study is that maternal hyperglycemia decreased H3Me3K36 of the IGF-1 gene in the same fashion that IUGR decreased this histone mark." (PMID 22548154, 2012). "The model we chose to study epigenetic profile of the IGF-1 gene is a well-characterized model of streptozotocin- (STZ-) induced maternal hyperglycemia." (PMID 22548154, 2012). "One limitation of this study is that maternal hyperglycemia was induced by STZ, and it is possible that STZ crosses the placenta and thus affects fetal and postnatal glucose levels, hepatic IGF-1 mRNA variant levels, and epigenetic characteristics." (PMID 22548154, 2012). "Maternal hyperglycemia decreased trimethylation of lysine 36 throughout the IGF-1 gene in males, and at exon 4 in females." (PMID 22548154, 2012). "Three of our four patients presented decreased GH and IGF-1 levels after being treated with only 4 mg rosiglitazone (the usual dose for hyperglycemia in México) for six months." (PMID 21600024, 2011). "Toxic effects of hyperglycemia on ovaries and/or increased IGF-1 levels might potentiate the effects of insulin on ovaries in women with prediabetes." (PMID 41384021, 2025). "This may be attributed to the fact that hyperglycemia activates the insulin-like growth factor-1 (IGF-1) and PI3K/AKT/mTOR pro-survival signaling pathways, thereby enhancing the resistance of tumor cells to treatment." (PMID 41357588, 2025).
Hyperglycemia (continued). "In addition, insulin and hyperglycemia stimulate IGF1 production, and the binding of IGF1 to its receptor activates the downstream signaling pathways that involve PI3K/AKT/mTOR and the RAS/RAF/mitogen-activated protein kinase (MAPK) pathways." (PMID 40430851, 2025). "Hyperglycemia may contribute to bladder carcinogenesis through impaired immune function, chronic inflammation, and activation of insulin and IGF-1 signaling pathways." (PMID 40647559, 2025). "Additionally, the downregulation of IGF1 via the ETS1/MMP1 pathway in this prediction model contributed to hyperglycemia, which has been validated by studies on the b-cells of diabetic transgenic mice." (PMID 39125657, 2024). "Moreover, hyperglycemia directly inhibits the production of IGF-158, and chronic hyperglycemia can suppress the secretion of growth hormone (GH), which in turn reduces IGF-1 production since GH stimulates its synthesis." (PMID 38531890, 2024). "In addition, hyperglycemia decreases sex hormone binding globulin, leading to elevated insulin-like growth factor-1 (IGF-1) and suppressed apoptosis." (PMID 37033267, 2023). "During hyperglycemia, miR-182-5p plays an essential role in suppressing gluconeogenesis by affecting insulin-like growth factor-1 (IGF1) and its receptor and subsequently stimulating the phosphoinositide-3-kinase-protein kinase/akt (PI3K/Akt) signaling pathway and FOXO1." (PMID 37108651, 2023). "Moreover, in mice, tumor necrosis factor-α (TNF-α) and insulin-like growth factor 1 (IGF1) promote the expression of glucose transporter protein type 1 (GLUT-1), causing hyperglycemia in the placenta, which accelerates the overgrowth of the fetus." (PMID 35267914, 2022). "When hyperglycemia occurs, insulin-like growth factor 1 (IGF-1) concentration increases." (PMID 35847887, 2022). "Hyperglycemia stimulates tumor growth by inducing the increase of insulin and IGF-1 levels." (PMID 35907868, 2022). "Hyperglycemia also affects the secretion and release of insulin and activates insulin-like growth factor 1 (IGF-1), which may promote the occurrence and development of tumors." (PMID 35463649, 2022). "IGF-1 signaling, together with insulin/insulin receptor signaling, mediates cellular proliferation and survival in multiple pathological conditions including hyperglycemia." (PMID 34371877, 2021). "Even though independent associations among hyperglycemia, ROP, and IGF1 have been described, a more detailed understanding of ROP risk, with specific levels of hyperglycemia during different postnatal weeks, the contribution of insulin insensitivity, and the role of IGF1, is needed." (PMID 33004691, 2020). "We found that hyperglycemia/hypoinsulinemia decreased revascularization and that IGF1 treatment improved revascularization, which is potentially novel and adds to the knowledge of how IGF1 treatment might help prevent ROP." (PMID 33004691, 2020). "However, the exact mechanism for the observed hyperglycemia as a side effect of IGF1 inhibitors is unclear, but cross-reactivity with the IRB, which is involved in the glucose metabolism, is likely to be an important factor." (PMID 33260481, 2020). "Therefore, even if IGF-1 reduces blood glucose, the decrease is only a maximum of 163 mg/dL (9.06 mmol/L); therefore, it is a limited treatment for marked hyperglycemia." (PMID 32337291, 2020). "Therefore, this is conceivable to conclude that the worsening effect of hyperglycemia on periodontal health in these patients was blurred by the concurrent presence of GH/IGF1 excess." (PMID 33154456, 2020). "Hyperglycemia, through ligands binding to insulin receptors, may increase circulating insulin-like growth factor-1 (IGF-1) levels." (PMID 30965609, 2019). "The effect of metformin on hyperglycemia decreases intracellular reactive oxygen species (ROS) and advanced glycation end-products (AGEs) in collagen, and reduced serum levels of insulin-like growth factors (IGF-1) were beneficial for bone formation." (PMID 31886264, 2019).
Hyperglycemia (continued). "The reason may be that the correlation between PSD and hyperglycemia is mainly related to insulin-like growth factor-1 (IGF-1), and blood glucose and immune factors can affect the level of IGF-1 in blood." (PMID 30181997, 2018). "In conclusion, our data indicates that continuous hyperglycemia might lead to an elevated expression of Grb10 and the subsequent decrease in IGF-1/IGF-1R signaling in kidneys, which may consequently contribute to the pathogenesis of diabetic nephropathy." (PMID 26986757, 2016). "However, whereas these mechanisms contribute to hyperglycemia, IGF-1, its peripheral target hormone, has opposing effects." (PMID 26514337, 2015). "Interestingly, Glut4 expression was mildly increased by hyperglycemia exposure, whereas IGF-1 levels were unchanged." (PMID 26064981, 2015). "Indeed, previous work in culture has revealed that hyperglycemia and IGF-1 can induce cellular senescence in fibroblasts." (PMID 25063774, 2014). "This enhancement occurs through a hyperglycemia induced increase in extracellular matrix production that increases the levels of ligands for integrin αVβ3 and permits phosphorylation of the adaptor protein, Shc, in response to IGF-1 stimulation." (PMID 24276258, 2013). "IGF-1 is a peptide growth factor that shares approximately 50% sequence homology with insulin and is produced primarily by the liver following stimulation mainly by growth hormone, as well as hyperinsulinemia and hyperglycemia." (PMID 23819063, 2013). "Maternal hyperglycemia decreased hepatic H3Me3K36 of the IGF-1 gene in DOL 21 OHM males." (PMID 22548154, 2012). "Therefore we examined the epigenetic profile of insulin-like growth factor 1 (IGF-1) in a well-characterized rat model of maternal hyperglycemia to determine if the epigenetic profile of IGF-1 is conserved in disparate models of in utero adaptation." (PMID 22548154, 2012). "Both hypoglycemia and hyperglycemia can interfere with retinal vascular development, hypoglycemia by limiting the available energy substrate and hyperglycemia through oxidative stress, inflammation, and altered expression of growth factors such as IGF-1 and VEGF." (PMID 41597382, 2026). "Importantly, higher IGF-1 correlates with better metabolic control, suggesting that maintaining adequate IGF-1 could be protective against both hyperglycemia and atherogenic lipid changes." (PMID 41393761, 2025). "This is thought to be due to low IGF-1 levels caused by the upregulated expression of insulin-like growth factor-binding protein (IGFBP-1) secondary to low portal insulin; this is the most likely mechanism of disease in our patient given his severe degree of hyperglycemia." (PMID 38793013, 2024). "However, as IGF1 levels remained stable in most patients following dose reduction, it should also be considered in patients with levels in the upper half of the normal range who have hyperglycaemia." (PMID 37530039, 2023). "Exposure of diabetic neurons to 5 mM D-glucose for 1 day also induced significantly higher levels of IGF-1 mRNA compared with the 25 mM D-glucose group, revealing that the inhibitory effect of hyperglycemia on endogenous IGF-1 gene expression could be relieved by transition to normoglycemia." (PMID 35298717, 2022). "Therefore, the systemic changes of IGF-1 might, in some extent, explain the mechanism of hyperglycemia and hyperketonemia on bone growth, bone development, and bone mass accrual." (PMID 33193101, 2020). "Cell proliferation evoked by Ins/IGF-1 largely depends on glucose concentration and the studies combining Ins or IGF-1 supplementation with hyperglycemia reported a faster proliferation rate." (PMID 40277891, 2025). "In addition, insulin may promote malignant transformation, cancer progression and metastasis through binding and activation of the IGF-1 receptor, and hyperglycaemia itself may increase cellular sensitivity to IGF-1, further contributing to cancer development and progression." (PMID 40357210, 2025).
Hyperglycemia (continued). "Nutritional aspects are also important in cancer post-treatment follow-up due to the modulation of hormonal levels related to cancer progression, such as the insulin-like growth factor-1 (IGF-1) and those induced by hyperglycemia and abdominal fat5,6." (PMID 38287041, 2024). "Hyperglycemia increases hypoxia-inducible factor-1 (HIF-1) and insulin-like growth factor-1 (IGF-1) in both the serum and the vitreous, leading to hypoxia, inflammation, and the consequent activation of glial cells." (PMID 37047550, 2023). "Hyperglycemia suppressed IGF-1 gene expression in cultured DRG neurons and this was reversed by exogenous IGF-1 or the aldose reductase inhibitor sorbinil." (PMID 35298717, 2022). "The inhibitory effect of hyperglycaemia on PI3K activity in HUVEC and its modulation with IGF-1 (10 ng/ml) were demonstrated by Western blotting for phoshorylation of Akt at Serine 473 (pAktSer473)." (PMID 34381074, 2021). "Hyperglycemia reduces IGFBP-2 expression in mesangial cells, exacerbating IGF1 effects on mesangial cells, and increases the expression of IGFBP-3, which mediates mesangial cell apoptosis." (PMID 34943879, 2021). "Interestingly, insulin/IGF may also stimulate normal cells that could assist in cancer progression, as hyperglycaemia allows IGF-1 to stimulate vascular smooth muscle cell proliferation and migration leading to abnormal vasculature growth, a hallmark of cancer." (PMID 34535145, 2021). "The hyperglycaemia elevates hypoxia induced factor 1 (HIF-1) and insulin-like growth factor 1 (IGF-1), both in the serum and the vitreous body of diabetic patients." (PMID 33504108, 2021). "We have found that post-natal growth was altered in babies who required insulin for idiopathic hyperglycemia of prematurity and that SGA neonates were likely resistant to GH and IGF1." (PMID 34447729, 2021). "However, the novelty aspect in this study is that the determination of morin effects on bone histomorphometry along with the suggestion of insulin/IGF-1 as another protective pathway by which morin might protect skeletal tissues from the deleterious effects of hyperglycemia." (PMID 34371877, 2021). "Apart from insulin and IGF1 (insulin-like growth factor 1) signaling, there is compelling evidence for the CRC-promoting role of hyperglycemia per se as cancer cells require high amounts of glucose due to the Warburg effect." (PMID 32971867, 2020). "IGF-1 resistance is suggested to be caused by pro-inflammatory cytokines, high IGF-1 concentrations, and hyperglycemia via IGF-1 signaling disturbances or lower IGF-1 bioavailability." (PMID 32458292, 2020). "In MetS, both hyperglycemia and hyperinsulemia increase bioavailable IGF-1 likely due to the suppression of IGBPs and increases in IGF-1 synthesis, respectively." (PMID 27349496, 2016). "Specifically, rat maternal hyperglycemia would decrease offspring promoter DNA methylation and alter multiple markers of the histone code from promoter 1 through the 3′UTR of the IGF-1 gene including increased H3Me3K36." (PMID 22548154, 2012). "In summary, our findings suggest that the PR-diet markedly reduced hyperglycemia and peripheral neuropathy in STZ-induced diabetic rats; and that this reduction was due to increased IGF-1 secretion and anti-oxidative stress enzyme HTase activation." (PMID 22194889, 2011). "The primary cause of the decline in ICC in diabetes was found to be reduced insulin and IGF1 signaling, rather than hyperglycemia." (PMID 37759758, 2023). "The reduction in insulin and IGF1 signaling, leading to a decline in the ICC and subsequent myopathy, has been identified as a key contributor to diabetic gastroparesis, distinct from the effects of hyperglycemia." (PMID 37759758, 2023). "on 190 patients recruited in eight European centers that did not demonstrate any adverse outcome for hyperglycemia or arterial hypertension in acromegalic patients with discordant GH/IGF-1 values, either in High GH or in High IGF-1 patients." (PMID 37829686, 2023).
Hyperglycemia (continued). "Hyperglycemia and AGEs accumulation in bone tissue matrix reduced the expression of IGF-1 receptors in osteoblast, thereby attenuating the response of osteoblast to IGF-1 even if the serum IGF-1 levels are normal." (PMID 36297386, 2022). "Suppression of endogenous IGF-1 in DRG cultures impedes background axonal outgrowth, and depletion of IGF-1 by a hyperglycemia-driven increase in polyol pathway activity which may contribute to neurodegeneration and suppress neurite outgrowth." (PMID 35298717, 2022). "A similar result was found in another experiment that involved IRS1 knockout mice lacking hepatic IRS2, it was observed that leptin, IGF1 levels was decreased, glucose tolerance ability was impaired and resulted in hyperglycemia." (PMID 35241081, 2022). "In preterm infants, other metabolic regulators like insulin-like growth factor-1 (IGF-1), adiponectin (APN) and FGF21 may better targets to control hyperglycemia." (PMID 36420952, 2022). "Hyperglycemia and retinal ischemia lead to the production of angiogenic factors, including vascular endothelial growth factor (VEGF), basic fibroblast growth factor (bFGF), platelet-derived growth factor (PDGF), insulin-like growth factor-1, and interferon-α." (PMID 34790415, 2021). "Hyperglycemia increases hypoxia induced factor 1 (HIF-1) and insulin-like growth factor-1 (IGF-1)." (PMID 34956981, 2021). "Patients with CAD and hyperglycemia are known to have lower IGF-1 levels .6,7,17,18 Therefore, our study population of hyperglycemic ACS patients can be expected to have relatively low baseline IGF-1 levels." (PMID 34851758, 2021). "The increased prevalence of any ROP and of severe ROP seen clinically and experimentally is possibly explained by decreased IGF1 expression mediated through decreased insulin signaling and not necessarily by hyperglycemia itself." (PMID 33004691, 2020). "A recent study demonstrated that brown fat transplantation reduces hyperglycemia in type 1 diabetes in mice, primarily through an increase in circulating IGF-1 and independent of insulin." (PMID 28854965, 2017). "While hyperglycaemia has been reported as a possible mechanism, it is not thought to be the primary candidate, with insulin-like growth factor 1 (IGF-1) believed to have a greater influence." (PMID 28376727, 2017). "We found that TRB3-short hairpin RNA (shRNA) lentiviral infection reduced TRB3 expression but did not change hyperglycaemia and plasma level of insulin or IGF-1." (PMID 26268733, 2015). "The alcoholic extract of D. bulbosum ameliorated hyperglycemia and diabetic complications in STZ-induced diabetic rats by inhibiting the expression of pro-angiogenic factors, including VEGF/VEGFR2, MMP 2/9, PDGF A/B, bFGF, and insulin-like growth factor 1 (IGF-1)." (PMID 39769940, 2024). "Hyperglycemia-induced activation of PKC and/or suppression of CaMKII and calcineurin might therefore contribute to impaired activity and binding of NFAT1 and CEBPβ to target the Igf1 gene promoter." (PMID 35298717, 2022). "The recommended strategy is to measure serum IGF-1 and in patients with elevated or equivocal serum IGF-1 levels, confirming the diagnosis by demonstrating an unsuppressed GH value ≥ 1 μg/L following documented hyperglycemia during an oral glucose tolerance test (OGTT)." (PMID 33803429, 2021). "However, the classification, comparison, and characteristics for each blood glucose pattern (hyperglycemia, hypoglycemia, or both hyperglycemia and hypoglycemia), statistical analysis, prognosis, and specific effects of IGF-1 have not been clarified." (PMID 32337291, 2020). "The early downregulation of liver Igf1 expression without affecting plasma glucose levels suggested a hyperglycemia-independent suppression of liver Igf1 mRNA expression in this model, likely due to the hypoinsulinemia resulting in decreased insulin signaling in the liver." (PMID 33004691, 2020).